PADI3 (peptidyl arginine deiminase 3)
Diseases named in the same sentence as PADI3 in open-access papers (continued):
Sharing a sentence is not in itself a finding about the gene and the disease.
cancer (17 papers, 2013 to 2025). A tumor composed of atypical neoplastic, often pleomorphic cells that invade other tissues. "Our findings suggested that the anti-cancer function of AT-II is associated with the suppression of glycolysis and induction of apoptosis by blocking the PADI3-ERK signaling pathway." (PMID 38474453, 2024). "CHD4 induces PADI1 and PADI3, causing pyruvate kinase isozyme M2 (PKM2) R106 citrullination that enhances serine activation, sustaining glycolysis under hypoxia and reshaping cancer cell proliferation." (PMID 41562091, 2025). "In multiple cancer cell types, PADI3 modulates PKM2 citrulline to contribute to increased glycolysis and cell proliferation." (PMID 38474453, 2024). "Here we show that CHD4 regulates expression of PADI1 (Protein Arginine Deiminase 1) and PADI3 in multiple cancer cell types modulating citrullination of arginine residues of the allosterically-regulated glycolytic enzyme pyruvate kinase M2 (PKM2)." (PMID 33741961, 2021). "PADI1 and PADI3 were co-ordinately regulated in multiple types of cancer cells and their expression was inversely related to that of CHD4." (PMID 33741961, 2021). "Here, the authors show that PKM2 citrullination by PADI1 and PADI3 lowers its sensitivity to metabolic inhibitors leading to increased glycolysis and reduced cancer cell proliferation." (PMID 33741961, 2021). "In conclusion, AT-II exerts anti-cancer activity by blocking the PADI3-ERK signaling pathway." (PMID 38474453, 2024). "PADI1 and PADI3 can promote glycolysis through citrulline pyruvate kinase M2 (PKM2) arginine 106, leading to the proliferation of cancer cells." (PMID 37020554, 2023). "This correlation was lower in cancers, such as bladder orf cervical that had higher intrinsic PADI1 and PADI3 expression." (PMID 33741961, 2021). "In human cancers, PADI1 and PADI3 expression is regulated by hypoxia stimulating PKM2 activity and contributing to the increased glycolysis seen under hypoxic conditions." (PMID 33741961, 2021). "We examined the correlation between the hypoxic signatures of several cancer types with PADI1 and PADI3 expression." (PMID 33741961, 2021). "PADI3 can affect the proliferation and invasion of tumor cells by regulating energy metabolism, EV and signal transduction (Sirt2/p21/AKT/Snail, Hsp90/CKS1), thereby inhibiting or promoting cancer." (PMID 37020554, 2023).
tumor (12 papers, 2019 to 2025). "PADI3 can also increase the invasiveness of tumor cells by mediating EVs, thereby promoting the malignant progression of PDAC." (PMID 37020554, 2023). "ZNF518B drives cell proliferation in CRC by silencing key tumor suppressors such as Peptidyl arginine deiminase 3 (PADI3) and Regulator of G protein signaling (RGS4)." (PMID 35740522, 2022). "Despite this strong co-regulation, no negative correlation with CHD4. was seen suggesting there may be alternative mechanisms regulating PADI1 and PADI3 co-expression in tumours." (PMID 33741961, 2021). "We speculated that PADI3 may plays its anti-tumor activity via suppress CKS1 induced cell proliferation." (PMID 31708688, 2019). "High expression of PADI2 and PADI3 can reduce the expression of moesin, increase extracellular vesicles (EVs) to release tumor-promoting factors, reduce EV tumor suppressors, and increase the invasiveness of tumor cells, thereby promoting the malignant progression of PDAC." (PMID 37020554, 2023). "Studies have shown that PADI2, PADI3 and PADI4 in the PADI family promote the carcinogenic microenvironment by mediating the formation of EVs, leading to tumor invasion." (PMID 37020554, 2023). "Among these genes, PADI3 (peptidyl arginase deiminase 3) and CDC42EP3 (CDC42 effector protein 3) are of particular interest because of their roles in macrophages and tumor biology." (PMID 31532791, 2019). "In several human tumours, PADI1 and PADI3 expression was positively correlated with hypoxia." (PMID 33741961, 2021).
adenocarcinoma (1 paper, 2020). A common cancer characterized by the presence of malignant glandular cells. "In vitro lung epithelial and adenocarcinoma alveolar cell models revealed that PADI1, PADI2 and PADI4 mRNA levels were elevated, but PADI3 and PADI6 mRNA levels were reduced in SARS-CoV-2-infected NHBE cells." (PMID 32629995, 2020).
neurodegenerative disease (1 paper, 2023). A disorder of the central nervous system characterized by gradual and progressive loss of neural tissue and neurologic function. "However, PADI2, PADI3 and PADI4 can also inhibit the progression of neurodegenerative diseases by participating in the differentiation, apoptosis and senescence of nerve cells." (PMID 37020554, 2023).
PADI3 also shares sentences with these, for which no sentence is quoted: interstitial lung disease (6 papers); fungal infection (3); glioblastoma (3); pancreatic cancer (3); astrocytoma (2); brain cancer (2); joint disease (2); lung disease (2); cicatricial alopecia (1); CNS tumours (1); colon adenocarcinoma (1); frontal fibrosing alopecia (1); hepatocellular carcinoma (1); homocystinuria (1); Joubert syndrome 23 (1); Lewy body disease (1); lung carcinoma (1); malignant glioma (1); metastatic carcinoma (1); multiple sclerosis (1); oral squamous cell carcinoma (1); pancreatic adenocarcinoma (1); Parkinson disease (1); rectal adenocarcinoma (1); triple-negative breast carcinoma (1); uveal melanoma (1).